ENSG00000238628
Synonyms: LOC124901528
Gene: Small nucleolar RNA gene on chromosome 6 (87,720,915 to 87,721,018, forward strand). Ensembl gene ENSG00000238628.
Gene Ontology:
Biological process: RNA processing
Cellular component: nucleolus
Homologues: Paralogues in human: SNORD13P3 (85% identical), SNORD13 (84% identical), SNORD13D (83% identical), SNORD13E (83% identical), SNORD13P1 (83% identical).